EGFR (epidermal growth factor receptor)
Diseases named in the same sentence as EGFR in open-access papers (continued):
Sharing a sentence is not in itself a finding about the gene and the disease.
lung adenocarcinoma (continued). "The best performing EGFR algorithm was attention-based and achieved an area under the curve (AUC) of 0.870, a negative predictive value (NPV) of 0.954 and a positive predictive value (PPV) of 0.410 in a validation cohort reflecting the 15% prevalence of EGFR mutations in lung adenocarcinoma." (PMID 36927889, 2023). "Among patients with brain relapse after complete resection of lung adenocarcinoma, patients with EGFR mutations might have intracranial relapse only without synchronous extracranial metastases." (PMID 37062064, 2023). "Also HLA-DPB1 and ROS1-DCBLD1 were associated with lung adenocarcinoma in EGFR mutation-positive cases stronger than in negative ones." (PMID 36817482, 2023). "Among patients with brain relapse after resection of lung adenocarcinoma, patients with EGFR mutations might have intracranial relapse only without synchronous extracranial metastases." (PMID 37062064, 2023). "However, since EGFR mutation is more likely to occur in female, non-smoking, non-emphysema lung adenocarcinoma patients, we only predict the EGFR mutation not T790M mutation in clinical practice." (PMID 37697337, 2023). "There is little summary of the clinical characteristics of patients with early lung adenocarcinoma; only females, the elderly, and nonsmokers may be more likely to develop EGFR gene mutations than other early lung adenocarcinoma patients." (PMID 37390230, 2023). "A previous comparative analysis between advanced- and early stage lung adenocarcinomas also confirmed that EGFR mutation was not correlated with gender, but the proportion of smokers in patients with early stage lung adenocarcinoma was higher than that in the advanced." (PMID 37924162, 2023). "The DD genotype is more frequent in lung adenocarcinoma patients without the EGFR mutation (22.6%)." (PMID 37371643, 2023). "However, we observed that patients with the DD genotype of ACE1 rs4646994 were less likely to have EGFR mutations in male and female subgroups of lung adenocarcinoma patients, which was consistent with the results of no gender stratification analysis." (PMID 37371643, 2023). "Epigenome factors may complement DNA mutation status to identify patients with lung adenocarcinoma who are unlikely to benefit from EGFR-TKI therapy." (PMID 36778111, 2023). "In this review, it was found that 66.7% of cases with immunotherapy-induced histological transformation were classified as lung squamous cell carcinoma (LSCC), while histological conversion into lung adenocarcinoma (LUAD) without EGFR or ALK gene mutations has rarely been reported." (PMID 38022621, 2023). "Finally, to further explore the advantages and drawbacks of the ISELA model one could compare it with mathematical models applied to the same context of use: patients with EGFR-mutant lung adenocarcinoma treated with first-generation TKI." (PMID 37524705, 2023). "Consequently, MMP11 is related to the immunological microenvironment of EGFR-mutant lung adenocarcinoma, which may be a predictor of possible immunotherapeutic response." (PMID 36756152, 2023). "Additionally, EMT can be a mechanism to induce EGFR-TKI resistance in lung adenocarcinoma." (PMID 37239162, 2023). "Herein, we aimed to develop and interpret robust optimal predictive models to identify EGFR mutation status and subtypes based on multi-center 18F-FDG PET/CT data, and further construct a prognostic model to predict clinical outcome in patients with lung adenocarcinoma." (PMID 37223682, 2023). "The EGFR mutation rate in female non-smokers with lung adenocarcinoma is approximately 50%." (PMID 35029237, 2022). "Further, as PLAUR overexpression was shown to induce gefitinib resistance through the EGFR/p-AKT/surviving signaling pathway in cell models of human lung adenocarcinoma, strategies that downregulate PLAUR could also be explored to avoid EGFR-targeted resistance mechanisms." (PMID 35480116, 2022).
lung adenocarcinoma (continued). "However, despite the widespread availability of KRAS and/or EGFR mutation testing, these genetic abnormalities have been discovered in a subset of resected lung adenocarcinomas and not in squamous carcinomas." (PMID 35454856, 2022). "The odds ratio of the EGFR Q787Q polymorphism could refer to advanced disease, but not all lung adenocarcinomas." (PMID 35387120, 2022). "All KRAS and EGFR mutations were observed in patients with lung adenocarcinoma (5/26 patients each, representing 31.25%) in accordance with previously published data showing KRAS mutations in 18–32% of ADKs and only 1.6–7.1% of SSCs and EGFR mutations in about one-third of ADKs and in 3–18% of SSCs." (PMID 36551569, 2022). "The aim of this study was to investigate the effects of different thoracic radiotherapy doses on OS and incidence of radiation pneumonia which may provide some basis for optimizing the comprehensive treatment scheme of these patients with advanced EGFR mutant lung adenocarcinoma." (PMID 36153486, 2022). "However, intensive EGFR L858R expression on micropapillary components may increase the recurrence of lung adenocarcinoma." (PMID 36011604, 2022). "This is the first known report to describe a case of advanced non-smoking lung adenocarcinoma with no epidermal growth factor receptor mutation after comprehensive epidermal growth factor receptor-tyrosine kinase inhibitor-based therapy that survived for nearly 12 years." (PMID 35029237, 2022). "Consequently, the GAS5 genotype analyses in patients with lung adenocarcinoma and EGFR wild type may be suggested to find advanced tumor condition." (PMID 36011604, 2022). "According to previous literature, the existence of EGFR L858R expression mutation may cause a better therapeutic outcome of lung adenocarcinoma without other genetic risk factors such as cytoplasmic ERβ1 expression." (PMID 36011604, 2022). "As a biomarker reflecting the systemic immune-inflammation status, the SII and its dynamic change may have a prognostic value in patients with EGFR-mutant lung adenocarcinoma treated with BM radiotherapy, which seemed to be a promising parameter for inclusion in future prognostic systems." (PMID 35241046, 2022). "Thus, we performed a systematic review and meta-analysis to investigate if specific clinical and computed tomography (CT) patterns could help to differentiate between EGFR in exon 21 and exon 19 in patients with lung adenocarcinoma." (PMID 35774697, 2022). "Interestingly, we observed significantly decreased L-scores and increased S-scores in lung adenocarcinoma samples with EGFR gene amplification but not in samples with EGFR gene mutations." (PMID 35016696, 2022). "We presented a 67-year-old nonsmoking female lung adenocarcinoma patient with novel epidermal growth factor receptor (EGFR) A289G/F287_G288insHA cis mutations who responded positively to sintilimab combined with regorafenib and albumin paclitaxel, and sequential treatment of icotinib." (PMID 35251994, 2022). "In addition, there is evidence that the expression of PLAUR is upregulated in fentinib-resistant lung adenocarcinoma cells, and PLAUR can induce gefitinib resistance in gefitinib-resistant human lung adenocarcinoma cells through the EGFR/p-AKT/survivin signaling pathway." (PMID 35675366, 2022). "Therefore, this study aimed to investigate whether the SII value before brain radiotherapy and its dynamic changes during brain radiotherapy were predictive for OS in patients with BMs from EGFR-mutant lung adenocarcinoma." (PMID 35241046, 2022).
lung adenocarcinoma (continued). "Therefore, the skewness and 10th percentile of first-order features at baseline level could be used to predict the efficacy in EGFR-mutant advanced lung adenocarcinoma following standard first-line EGFR-TKI therapy." (PMID 36052262, 2022). "We reported an unusual case of metastasis to the breast from epidermal growth factor receptor (EGFR)-mutated and estrogen receptor (ER)-positive lung adenocarcinoma and provide a review of the literature focused on the breast as metastatic site from EGFR-mutated lung adenocarcinoma." (PMID 34590588, 2021). "Therefore, increasing the TSHZ2 expression in EGFR wild-type patients with lung adenocarcinoma might be a viable alternative treatment option." (PMID 33850468, 2021). "Finally, changes in plasma HMGB1 from a cohort of lung adenocarcinoma patients without EGFR mutation and treated with cisplatin-based therapy were analyzed." (PMID 34966671, 2021). "Interestingly, based on our data, almost half of lung adenocarcinoma cases with EGFR gene mutations were female with no tobacco exposure." (PMID 34181354, 2021). "Therefore, this study aimed to explore the association between VM and the response to anticancer therapy in patients with lung adenocarcinoma and to examine the difference between TKIs and platinum-based regimen as first-line therapy in EGFR-mutant lung adenocarcinoma with VM." (PMID 33549061, 2021). "In addition, we assessed the associations between WWOX SNPs and the clinicopathological factors in lung adenocarcinoma patients with or without EGFR mutations." (PMID 34948746, 2021). "Here, we report a case of stage IVB lung adenocarcinoma without EGFR mutation at initial diagnosis." (PMID 33578601, 2021). "Finally, changes in plasma HMGB1 levels in a cohort of lung adenocarcinoma patients without EGFR mutations and treated with CDDP-based chemotherapy were determined." (PMID 34966671, 2021). "However, to the best of our knowledge, clinical trials evaluating BTAs specifically in EGFR-mutated lung adenocarcinoma do not exist." (PMID 34201833, 2021). "Furthermore, EphB4 turned out to be a significant poor prognostic factor in EGFR mutation-positive lung adenocarcinoma patients but not in EGFR mutation-negative patients." (PMID 34445227, 2021). "Therefore, we analyzed the genetic profiles of 131 patients with stage I to stage IIIA EGFR-mutated lung adenocarcinoma using NGS and compared the risk of recurrence based on co-occurring actionable mutations, the number of co-mutations, EGFR mutation types, and 19-del subtypes." (PMID 34298845, 2021). "However, it remains unclear whether the NOIR-SS has equivalent sensitivity and accuracy in detecting mutant EGFR ctDNA in patients with advanced lung adenocarcinoma as that of ddPCR." (PMID 34294857, 2021). "Therefore, miR‐1 could be a clinically useful marker to predict therapeutic efficacy of immunotherapy in lung adenocarcinoma patients with EGFR‐TKI resistance." (PMID 33305905, 2021). "Epidermal growth factor receptor (EGFR)-activating mutations [exon 19 deletion mutation and exon 21 L858R substitution mutation (L858R)] are the most and second most frequently identified driver alterations of lung adenocarcinoma in East Asian and Western countries, respectively." (PMID 34294857, 2021). "In this way, the frequent EGFR mutation in lung adenocarcinomas with MLCs may be due to the lung adenocarcinoma itself rather than the MLCs." (PMID 34234879, 2021). "Therefore, it was rationalized that TKIs could induce to antitumor activity in the EGFR-mutant lung adenocarcinoma cells through the inhibition of survival signaling." (PMID 34367939, 2021).
lung adenocarcinoma (continued). "The frequency of CD63–BCAR4 in lung adenocarcinoma without EGFR and KRAS mutations could be estimated as approximately 3% based on the present study (1/29) and Wang’s study (1/33); however, it might be much lower in Caucasians and/or in smokers." (PMID 33204025, 2021). "In addition, EphB4 had a significantly negative impact on the prognosis/clinical outcome in EGFR mutation-positive lung adenocarcinoma patients." (PMID 34445227, 2021). "While the inclusion of the mutational status of relevant genes to lung adenocarcinoma (e.g., EGFR) could have revealed important insight, the lack of this information in the majority of the studies and the resultant limited sample size hampered this aim." (PMID 33526761, 2021). "Indeed, in EGFR/MET mice, this combination increased survival, decreased tumor burden and reduced the expression levels of all the tested key proteins implicated in lung adenocarcinoma (pEGFR, pMET, pAKT and pERK), compared with the single treatments or vehicle." (PMID 34298655, 2021). "Furthermore, two patients with stage IV lung adenocarcinoma detected with EGFR exon 19 deletion and either concurrent KRAS K117N (n = 1) or concurrent de novo EGFR T790M (n = 1) achieved partial response with A+T regimen, with PFS of > 16.0 months and 10.3 months, respectively." (PMID 34663309, 2021). "However, even with EGFR-TKI use almost a quarter of the patients experienced SREs in this study, and in other studies, the reported frequency of SREs is even higher (37.3% to 58%) in patients with EGFR-mutated lung adenocarcinoma mainly treated with EGFR-TKIs." (PMID 34201833, 2021). "However, unlike other cancer types, active genetic mutation types such as epidermal growth factor receptor (EGFR) mutations in lung adenocarcinoma are not well understood in MPM." (PMID 33381446, 2020). "Furthermore, in addition to the clinical and pathologic characteristics investigated in our study, other factors such as smoking status, EGFR mutation status, KRAS mutation status may also affect the survival of patients with lung adenocarcinoma." (PMID 32207885, 2020). "Moreover, the co-existence of EGFR gene mutations, ALK gene fusions, and ROS1 gene rearrangements has been reported in a few lung adenocarcinoma cases, but the co-alteration of ROS1, EGFR, and EML4-ALK in MPA remains unclear." (PMID 32677962, 2020). "In addition, further studies are still required to study whether miR‐195 and LINC00461 expressions are associated with the presence of KRAS and EGFR in lung adenocarcinoma and to better elucidate the modulatory role of KRAS and EGFR in NSCLC." (PMID 31967713, 2020). "Together, the findings of the FLAURA trial and preclinical studies may support the results of our study: that PD-L1 expression does not affect the efficacy of EGFR-TKIs or survival in untreated stage IV EGFR-mutated lung adenocarcinoma patients." (PMID 32092879, 2020). "Metabolic syndrome also has been linked to the development of lung adenocarcinoma, especially in never-smokers, as genome-wide association studies (GWASs) have demonstrated that EGFR, VTL1A, TNFRSF10C, C3ORF21 and hyper-methylations of TNFSF10C, BHLHB5 and BOLL are involved in both pathways." (PMID 32104210, 2020). "Therefore, we clarified whether accurate evaluation of EGFR networks can predict the prognosis of early-stage lung adenocarcinoma." (PMID 32277151, 2020). "For instance, the discovery of the frequent mutation of EGFR in NSCLC especially lung adenocarcinoma in non-smoking female Asia patients leading to the development of generations EGFR-TKI (tyrosine kinase inhibitors) treatment, which has been showing effective results." (PMID 32795325, 2020). "Therefore, in this retrospective study, we aimed to evaluate whether 18F-FDG PET/CT and common clinicopathological features could predict EGFR status in advanced lung adenocarcinoma with histologically confirmed bone metastasis." (PMID 32742498, 2020).
lung adenocarcinoma (continued). "Consequently, the distribution of CA9 SNP and EGFR phenotypes is possible and may have a certain effect on the progression of lung adenocarcinoma, which is supported by the results of the current study." (PMID 32365566, 2020). "This study presents strong evidence that EGFR lowered expression in skin samples from stage IV lung adenocarcinoma patients treated with tyrosine kinase inhibitors could potentially be used as a surrogate to predict treatment response and avoid tumor biopsy‐related risks in this population." (PMID 33015988, 2020). "Additionally, clinical data demonstrated that high Mig-6 expression is a predictor of poor prognosis in lung adenocarcinoma patients with and without EGFR mutation." (PMID 32552717, 2020). "Therefore, targeting Mig-6 with EGFR-TKIs may be an effective strategy for killing EGFR-TKI-resistant lung adenocarcinoma." (PMID 32552717, 2020). "In support of this hypothesis, we observed that patient B_203 developed an lung adenocarcinoma about 1 year after an initially negative diagnosis, but a mutation on EGFR was already detected in the initial BW analysis." (PMID 32441866, 2020). "Our findings concerning FGFR4 SNPs rs2011077 and rs351855 may suggest a lower risk of tumor distant metastasis and FGFR4 gene expression levels may help the prediction of survival rates in Taiwanese lung adenocarcinoma patients, especially those bearing the wild-type EGFR gene." (PMID 32781755, 2020). "Furthermore, we studied the effect of FGFR4 SNPs on the clinicopathological characteristics of lung adenocarcinoma with and without EGFR mutation." (PMID 32781755, 2020). "During phase II trials, responses were more likely in patients with lung adenocarcinoma who were female, never-smokers, and of Asian origin; and it was not until 6 years later that EGFR mutations were published as biomarkers of response to EGFR inhibitors." (PMID 33364187, 2020). "AXL expression displays a positive correlation with PD-L1 expression in lung adenocarcinoma with epidermal growth factor receptor (EGFR) mutation, and abolition of AXL kinase activity inhibits PD-L1 mRNA expression in a lung adenocarcinoma cell line with EGFR mutation." (PMID 32403421, 2020). "This study included only lung adenocarcinoma and did not include EGFR mutation-positive samples." (PMID 33425389, 2020). "In the present study, we addressed whether the T790M mutation can evolve spontaneously without any TKI therapy in mice with lung adenocarcinoma harboring the L858R EGFR mutation." (PMID 33096790, 2020). "The aim of this study is to explore if and how EGFR mutation status affects the biological behavior of lung adenocarcinoma by detecting the DNA content and aneuploid peaks of advanced lung adenocarcinoma cells with or without EGFR mutations in the absence of EGFR-TKIs." (PMID 32127953, 2020). "Therefore, it is unknown whether targeted therapies such as EGFR-TKI could achieve similar response in primary myoepithelial carcinoma as in lung adenocarcinoma." (PMID 32505185, 2020). "In addition, an increased EGFR copy number occurred in three lung adenocarcinoma patients." (PMID 32711494, 2020). "Furthermore, the CA9 SNP rs2071676 is significantly correlated to both a lower tumor stage and lower risk for developing lymph node metastasis, whereas in the whole population of the male subgroup of lung adenocarcinoma, these results are mainly accompanied with the EGFR wild type." (PMID 32365566, 2020). "Therefore, considering the similar profile of somatic variations in ASC and lung adenocarcinoma, TKI might be an effective targeted agents for lung ASC with EGFR mutations." (PMID 33679868, 2020). "The two most frequent oncogenic mutations in lung adenocarcinoma, which are generally mutually exclusive, include the activating mutations in a small GTPase transductor protein KRAS (V-KI-ras2 Kirsten rat sarcoma viral oncogene homolog) and the epidermal growth factor receptor (EGFR)." (PMID 30832375, 2019).